RNU6-700P (RNA, U6 small nuclear 700, pseudogene)
Gene: Small nuclear RNA gene on chromosome 12 (9,624,122 to 9,624,228, reverse strand). Ensembl gene ENSG00000212345.
Homologues: Orthologues: macaque U6 (93% identical), mouse Gm26133 (67% identical), mouse Gm22476 (66% identical), guinea pig U6 (64% identical), rabbit U6 (60% identical), rat LOC120099053 (57% identical). Paralogues in human: RNU6-22P (80% identical), RNU6-39P (80% identical), RNU6-43P (80% identical), RNU6-1029P (79% identical), RNU6-1031P (79% identical), RNU6-1124P (79% identical), RNU6-1237P (79% identical), RNU6-140P (79% identical), RNU6-16P (79% identical), RNU6-17P (79% identical), RNU6-18P (79% identical), RNU6-25P (79% identical), and 1288 more.